TGFB1 (transforming growth factor beta 1)
Diseases named in the same sentence as TGFB1 in open-access papers (continued):
Sharing a sentence is not in itself a finding about the gene and the disease.
lung carcinoma (continued). "Given the fact that HOXC8 regulates TGFβ1 transcription in lung cancer cells, we analyzed the effects of TGFβ1 on cell proliferation, anchorage-independent cell growth and cell migration in A549 and NCI-H460 cells." (PMID 29367650, 2018). "TGFβ-1 induces a more aggressive in vitro phenotype in certain cancer cell lines, including the human lung carcinoma line A549 and the human pancreatic carcinoma line Panc-1." (PMID 29930202, 2018). "Consistently, we further showed that knockdown of HOXC8 significantly inhibited proliferation, anchorage-independent cell growth and migration of lung cancer cells, which can be rescued by ecto-expression of TGFβ1." (PMID 29367650, 2018). "In NSCLC, the TGFβ/TGFR pathway is considered as a tumor promoter, and the increasing TGFβ1 expression by tumor cells correlated with tumor progression and metastasis in lung cancer." (PMID 25149540, 2014). "In those studies, TGFβ1 expression in primary lung cancer tissues was higher among patients with pulmonary metastases than that among patients without such metastases." (PMID 23840350, 2013). "This prophylactic effect of rhubarb on lung cancer patients treated with radiotherapy has been explained by decreasing the level of transforming growth factor-beta-1 and interleukin-6." (PMID 24280678, 2012). "To investigate EMT in human lung carcinoma A549 cells, we treated cells with TNFα (20 ng/ml) and TGFβ1 (10 ng/ml) for 72 h." (PMID 22675434, 2012). "In the present study, human lung carcinoma A549 cells were treated with TNFα and TGFβ1 to induce EMT." (PMID 22675434, 2012). "In conclusion, we report that the induction of EMT by TGFβ-1 treatment in a primary lung cancer cell line results in the acquisition of mesenchymal profile and in up-regulation of the expression of stem cell markers." (PMID 21738704, 2011). "The induction of EMT by TGFβ-1 exposure, in primary lung cancer cell line results in the acquisition of mesenchymal profile and in the expression of stem cell markers." (PMID 21738704, 2011). "Finally, we applied ARTEMIS to an Epithelial-to-mesenchymal (EMT) dataset of A549 lung cancer cells treated with TGFB1, spanning five timepoints." (PMID 40662824, 2025). "Interestingly, Tgfβ1 has also been reported to positively regulate Mettl3 expression in lung cancer cells, thereby inducing EMT." (PMID 41360769, 2025). "However, polysaccharides have also shown an anticancer effect, suppressing Transforming Growth Factor-beta 1 (TGF-β1)-induced epithelial-to-mesenchymal transition in A549 lung cancer cells." (PMID 39519575, 2024). "A very similar mechanism involves MIR4435-2HG that is highly expressed in NSCLC, which was bioinformatically predicted to sponge distinct miRNAs that can target the TGFB1 mRNA, thus indirectly enhancing TGF-β signaling that was required for lung cancer cell proliferation and migration." (PMID 38571882, 2024). "Furthermore, ectopic expression of miR-200c in H460 lung cancer cells increases the percentage of hybrid E/M cells from ~5% to ~20% and these hybrid cells have increased responsiveness to external stimuli such as TGFβ1." (PMID 39409910, 2024). "Moreover, enhanced expression of EMT-related genes and proteins in the presence of TGFβ1 was observed in PGC1α-silenced A549 lung cancer cells." (PMID 35897813, 2022). "The expression of PTHLH is upregulated in TGFβ1-treated breast and lung cancer cells." (PMID 35406121, 2022). "Based on these findings, we hypothesized that TGFβ1-primed tumour cells exhibit PTHrP expression in lung cancer cells." (PMID 35406121, 2022).
lung carcinoma (continued). "The results of our transactivation assays show that TGFβ1 exposure up-regulates the transcriptional activity of ACSL3. mTORC1 signaling pathway has been reported to mediate the up-regulation of ACSL3 expression in mutant KRAS lung cancer cells." (PMID 35414781, 2022). "TGFβ1 induced AMPK phosphorylation in the human lung cancer A549 and H1460 cell lines." (PMID 36551653, 2022). "To understand the physiological relevance related to how decreased PGC1α, FOXA1, and ID1 promote metastasis via EMT in lung cancer, we speculated that TGFβ1, as a major EMT stimulus, could affect the suppression of PGC1α, FOXA1, or ID1." (PMID 35897813, 2022). "ID1, downstream of PGC1α and FOXA1, was also downregulated in TGFβ1-treated lung cancer cells." (PMID 35897813, 2022). "This suggests that PTHLH is a critical component for TGFβ1-induced cachexia in lung cancer." (PMID 35406121, 2022). "Additionally, TCF4 interacts with TWIST1, promotes EMT and TGFβ1 signalling, and subsequently enhances bone metastasis in KrasG12V-driven lung cancer." (PMID 35406121, 2022). "Consequently, PPARγ activation in macrophages has been shown to fuel lung cancer progression and metastasis, especially through increased arginase 1 and TGFβ1 expression." (PMID 35954274, 2022). "Mechanistically, integrin β3 is induced by increased levels of TGFβ1 in acquired TKI-resistant lung cancer, which indicates the TGFβ1/integrin β3 axis as a potential target for combination therapy in EGFR-mutant lung cancer to overcome acquired resistance to EGFR TKIs." (PMID 34976811, 2021). "Additionally, after radiotherapy the proliferation of lung cancer cells that had been co-cultured with TGFβ1-knockdown CAFs was greater than that of the TGFβ1-overexpression CAFs." (PMID 34095135, 2021). "Resveratrol presented inhibitory action against TGFβ1-induced EMT in lung cancer cells." (PMID 34220337, 2021). "For instance, SCUBE3 (signal peptide-CUB-EGF-like domain-containing protein 3), a secreted glycoprotein promoting lung cancer invasiveness, also binds to TβRII and TβRI, activates TGF-β/Smad2/3 signaling, up-regulates the expression of target genes such as TGFB1, and triggers EMT." (PMID 33478130, 2021). "Moreover, more complex mechanism of TGFβ1 expression in CAFs affecting the apoptosis of lung cancer cells requires further research." (PMID 34095135, 2021). "In lung cancer, it has been proven that dioscin inhibits TGFβ1-induced cell migration and invasion." (PMID 33061803, 2020). "TGFβ1 signaling is a critical driver of collagen accumulation in pulmonary fibrotic diseases and a well-characterized regulator of cancer associated fibroblasts (CAF) activation in lung cancer." (PMID 32943605, 2020). "Given the considerably activation of TGFβ1 signaling during lung cancer progression, we hypothesized that NSCLC might be also associated with the long-term PM2.5 exposure." (PMID 32554855, 2020). "In primary lung cancer cells, the induction of EMT by TGFβ-1 exposure was associated with a reduction in cell-cell adhesion and expression of mesenchymal markers, such as Slug, Twist and β-catenin, as well as an upregulation of the expression of stem cell markers." (PMID 31344049, 2019). "In addition to medical treatment, BBR has protective effects on radiation-induced lung injury via intercellular adhesion molecular-1 and transforming growth factor-beta-1 in patients with lung cancer." (PMID 31208348, 2019). "In prostate cancer cell lines, leptin treatment increased TGFB1 secretion 2-3-fold in a time and dose dependent manner, and in A549 lung cancer cells, leptin exposure increased TGFB1 expression, enhanced metastasis and EMT induction that was inhibited by siRNA against TGFB1." (PMID 28542577, 2017). "Furthermore, genomic studies on TGFβ-regulated gene expression profiles also suggest that in the human lung cancer cell line A549, TGFβ1 induces TG2 expression by a pathway that is partially dependent on the ERK signalling pathway." (PMID 28223538, 2017).
lung carcinoma (continued). "Through these experiments, we found that TNFα and TGFβ1 may have different roles in these human lung cancer cells." (PMID 22675434, 2012). "The significant SNPs in the TGFB1 promoter region may be related to abnormal TGFB1 gene transcription levels in lung cancer patients." (PMID 23094028, 2012). "In lung cancer, genetic variants in cytokine genes, such as IL6, IFNG, and TGFβ1, have been found to be associated with an increased severity of CRS after treatment with PD-1 inhibitors, suggesting that these biomarkers may help to predict the exacerbated inflammatory response." (PMID 40004863, 2025). "Moreover, common signaling pathways also play roles in both diseases, for example, deregulated PIK3/AKT pathway contributed to IPF and lung cancer by activating downstream molecules like Transforming Growth Factor Beta 1 (TGF-β1), which is known as a profibrotic mediator." (PMID 34767608, 2021). "Thus, we guess that TGFβ1/Smad signaling could be associated with PGC1α to finetune ID1-TCF4-TWIST1 transcriptional axis regulating EMT and lung cancer metastasis." (PMID 33917757, 2021). "Furthermore, we isolated F4/80+ TAMs from PBS- or HCQ-treated mice with orthotopic lung cancer, and we found that the M1-like molecules (Nos2, Ifng, IL12b,and IL1b) were up-regulated and the M2-like molecules (Arg1, Tgfb1, IL10, and Ido1) were down-regulated with HCQ treatment." (PMID 30373678, 2018). "Interestingly, a study in A549 lung carcinoma cells showed that MDA-9 might also prevent caveolin-1-mediated internalization of TGFβR1 leading to enhanced canonical TGFβ1 signaling." (PMID 27863394, 2016). "TGFβ1 signalling may also contribute to erlotinib response in lung cancers." (PMID 22045191, 2012). "In contrast, the MIR100HG gene that was described in the lung cancer section was transcriptionally induced by TGF-β and formed a feed-forward signaling loop by facilitating TGFB1 mRNA stabilization and growth factor secretion by prostate cancer cells." (PMID 38571882, 2024). "For TGFB1, Ki-Eun Hwang confirmed that TGF-β1 induces EMT, which leads to lung cancer cell migration and invasion." (PMID 38791306, 2024). "CD9 and CD81 are KLF4 transcriptional targets, regulating KLF4-CD9/CD81-JNK signaling pathway and TGFβ1/SMAD signaling pathway, indicated some KLFs via different mechanisms play important roles in inhibiting the growth of lung cancer." (PMID 38560274, 2024). "According to research, miRNA-183 can restrict PDCD4 expression and hence prevent the apoptosis of transforming growth factor beta 1-induced human hepatocellular carcinoma cells, also miRNA-183 is suggested to restrict FOXO expression in lung cancer." (PMID 37808196, 2023). "Some of the altered genes are already serving as treatment targets, e.g., PDL-1, ITBG2, TGFB1, and c-JUN, in many cancer types, including lung cancer." (PMID 37568601, 2023). "In the present study, we found that TGFβ1, an essential EMT-promoting factor, suppresses PGC1α and FOXA1 expression in various lung cancer cells." (PMID 35897813, 2022). "Consistent with the findings of previous studies, the expression of PTHLH was significantly upregulated in TGFβ1-treated A549, NCI-H1299, NCI-H1650, NCI-H358, L132, Calu-1, and Calu-3 lung cancer cells." (PMID 35406121, 2022). "For instance, TGFβ1 has been shown to induce decrease expression of DNA-methyltransferase 1 (DNMT1) and PD-L1 promoter demethylation, leading to PD-L1 overexpression in lung cancer cells that were undergoing EMT." (PMID 34381456, 2021). "Epicatechin-3-gallate (ECG) is involved in the TGFβ1-dependent EMT through overexpression of E-cadherin and inhibition of mesenchymal proteins in lung cancer cells." (PMID 34220337, 2021). "Next, to identify the specific source of TGF-β at the cellular level, we analyzed the expression of TGFB1, TGFB2, and TGFB3 using the sc-RNAseq datasets of 33K PBMC and 52K lung cancer cells." (PMID 35069521, 2021).
lung carcinoma (continued). "Downregulation of HTRA3 was noted in ovarian tumors, endometrial and lung cancers, and antagonism of HTRA3 and TGFβ1 (Tumor growth factor Beta) contributes to metastasis of non-small cell lung cancer." (PMID 32560402, 2020). "In A549 lung cancer cells, EGCG treatment determined TGFβ1-mediated EMT inhibition by suppressing the acetylation of Smad2 and Smad3." (PMID 31480720, 2019). "In certain NSCLC cells, we observed similar results of TGFβ1-induced EMT and generation of lung cancer stem-like cells." (PMID 29995950, 2018). "What’s more, CXCR7/TGFβ1 coexpression was positively correlated with the expression of CD44, a cancer stem cell marker promoting lymph node metastasis in lung cancer." (PMID 30574021, 2018). "Transwell assays further showed that knockdown of TGFβ1 significantly inhibited the migration of A549 or NCI-H460 cells, and TGFβ1 ecto-expression enhanced the migration of lung cancer cells." (PMID 29367650, 2018). "The second mechanism of MET regulation by TGFβ1 is related to suppression of miR‐128‐3p which, in turn, directly targets MET, which is in line with Jiang and colleagues non‐small cell lung cancer, and thereby impairs HGF/MET‐mediated cell migration." (PMID 30004628, 2018). "Furthermore, TGFβ1/SMAD3 activation, a fibrotic phenotype and nintedanib resistance were shown to be more strongly related to ADC than to SCC in lung carcinoma." (PMID 39075612, 2024). "Gene expression analyses in A549 JUNB WT and mut cell clones and in A549 JUNB-ER and control cells, however, failed to confirm that JUNB played a role in the TGFβ1-mediated regulation of these genes in the lung cancer cell line." (PMID 36672507, 2023). "In addition, ectopic FOXA1 expression significantly reversed TGFβ1-mediated expression of EMT markers, such as CDH1, CDH2, VIM, SNAI2, and PTHLH, in A549 lung cancer cells." (PMID 35897813, 2022). "TGFβ1-induced PTHLH expression was mitigated in TCF4-silenced A549 and Calu-1 lung cancer cells." (PMID 35406121, 2022). "Human lung cancer cell A549 was cultured with or without ppTGFβ1 or commercial TGFβ1 (10 ng/ml) for 48 h." (PMID 35712604, 2022). "Da Fonseca and colleagues investigated whether piperine may control transforming growth factor beta 1 (TGF-β1), which is a potent EMT inducer, in A549 lung cancer cells." (PMID 33256185, 2020). "In this study, we hypothesize a cooperation between TGFβ-1 and miRNAs and, in particular, hsa-miR-21 in the regulation of EMT in lung cancer cells." (PMID 31344049, 2019). "Similarly, microvesicles produced by hypoxic lung carcinoma and CML cells attenuated NK cell antitumor responses in vitro, presumably via transforming growth factor beta 1 (TGF-β1) and miR23a." (PMID 31535086, 2019). "Our hypothesis of a cooperation of TGFβ-1 and miRNA in inducing EMT in lung cancer cells is supported by different observations." (PMID 31344049, 2019). "Although E-cadherin did not exhibit significant changes in expression in A549 lung cancer cells after the application of TGFβ1, this was assumed to be due to the length of the time stamps used to measure their expression." (PMID 29467444, 2018). "We here found that, in lung cancer, Sp1 could form an auto-regulatory loop with TGF-β1, which enhanced TGFB1 transcription and TGF-β-induced EMT." (PMID 27829234, 2016). "High TGFβ1 expression represents an important prognostic parameter after surgical resection for patients with NSCLC; indeed, TGFβ1 plays critical and essential roles in the tumor progression and metastasis of lung cancers." (PMID 25149540, 2014). "Moreover, recent single‐cell analyses in ovarian and lung cancers demonstrate that tip‐like ECs exhibit induced TGFβ1 expression in response to tumour‐derived cues, rather than spontaneous production." (PMID 41431249, 2025).
lung carcinoma (continued). "Moreover, it was reported that transforming growth factor β1 (TGFβ1) induces decreased expression of DNA methyltransferase 1 (DNMT1) and PD-L1 promoter demethylation, which subsequently results in PD-L1 overexpression in lung cancer cells undergoing epithelial-mesenchymal transition (EMT)." (PMID 31258527, 2019).
hepatocellular carcinoma (884 papers, 1997 to 2026). A malignant tumor that arises from hepatocytes. "In hepatocellular carcinoma, TGFB1 caused redox imbalance, increasing the intracellular ROS level to promote ferroptosis." (PMID 38509680, 2024). "There is also compelling evidence for genetic predisposition to hepatocellular carcinoma and TGFB1 gene is one of promising candidates." (PMID 27835897, 2016). "To explore the possible causal association between circulating TGF-β1 and hepatocellular carcinoma, we thereby chose TGFB1 gene C-509T polymorphism as an instrument and conducted a meta-analysis of available published studies under the principles of MR method." (PMID 27835897, 2016). "This meta-analysis was designed to explore the causal association between circulating TGF-β1 and hepatocellular carcinoma by choosing TGFB1 gene C-509T polymorphism as an instrument under the principles of MR method." (PMID 27835897, 2016). "A candidate gene would be LOXL4, a target of TGF-β1 found to cause reduction in TGFβ1-mediated cell motility of hepatoma cells." (PMID 23408952, 2013). "Several molecular epidemiological studies have shown an association of TGFB1 SNPs with risk of various cancers, including breast, prostate and hepatocellular carcinoma and gastric cancer." (PMID 19835575, 2009). "Current literature is proliferating with a large volume of findings highlighting the susceptible role of TGFB1 gene in hepatocellular carcinoma; however, there is little published knowledge revolving the genetic determinants of circulating TGF-β1 and their possible relationship with this disease." (PMID 27835897, 2016). "For example, in hepatocellular carcinoma cells, TGFβ1 upregulates MMP2 via Smad3, boosting invasiveness." (PMID 40646747, 2025). "Coculture of fibroblasts treated with a TGFR1 inhibitor for 3 days with epithelial hepatoma cells confirmed that fibroblast-derived paracrine TGFb1 is sufficient for the acquisition of metastatic ability by epithelial hepatoma cells." (PMID 40253402, 2025). "The intricate interplay between cancer cells and the tumor microenvironment, coupled with the liver’s central role in TGFB1 clearance, highlights the dynamic nature of TGFB1 in the hepatocellular cancer." (PMID 39555097, 2024). "In hepatocellular carcinoma, however, E-cadherin is inhibited due to the action of Transforming Growth Factor Beta 1 (TGFβ)." (PMID 31717324, 2019). "In this study, we aimed to evaluate the suppressive effect of nano-formulation of curcumin developed in our laboratory on the hTERT gene expression via the induction of TGFβ1 signaling pathway in Huh7 cells, as a hepatocellular carcinoma cell line." (PMID 28992682, 2018). "In the current study, we aimed to explore suppressive effects of nanocurcumin on telomerase expression through TGFβ1 pathway in a hepatocellular carcinoma cell line (Huh7)." (PMID 28992682, 2018). "Starvation-mediated autophagy is critical for cellular invasion via EMT activation in hepatocellular carcinoma cells, and TGFβ1 stimulates EMT and autophagy via the activation of Smad signaling in cancer cells." (PMID 29844404, 2018). "The fifth limitation was that only one promoter polymorphism in TGFB1 gene was selected as an instrument and it is encouraging to see whether this polymorphism in combination with another functional locus will enhance risk prediction for hepatocellular carcinoma." (PMID 27835897, 2016). "Second, we examined the respective expression levels of miRNA-122, TGFβ1 and TGFβR1 in human and mouse hepatocellular carcinoma samples." (PMID 26987776, 2016). "When MHCC97-H and MHCC97-L cells were used as control groups in the experiment, our data suggested that hMSC inhibited hepatoma cells migration and made metastatic potential decrease, especially TGFβ-1 genetically modified hMSC." (PMID 26003220, 2015). "The proliferation ability effects of hMSC and TGFβ-1 infected hMSC on hepatoma cells (MHCC97-H and MHCC97-L) were detected using CCK-8 (Cell Counting Kit-8) assay." (PMID 26003220, 2015).